FGF23 (fibroblast growth factor 23)
Diseases named in the same sentence as FGF23 in open-access papers (continued):
Sharing a sentence is not in itself a finding about the gene and the disease.
hyperphosphatemia (continued). "The importance of α-KL for FGF23 signaling in the kidney is apparent in Klotho- and Fg23-null mice, which share nearly identical biochemical phenotypes that are consistent with the dismantling of FGF23 signaling, including hyperphosphatemia and elevated 1,25VitD3." (PMID 24466013, 2014). "As CKD progresses, the ability to compensate for elevations in parathyroid hormone (PTH) and fibroblast growth factor-23 and for decreases in 1,25(OH)2D3 becomes inadequate, which results in hyperphosphatemia, abnormal bone disorders, and extra-skeletal calcification." (PMID 24587915, 2014). "However, effective removal of FGF-23 in MHD patients exhibiting hyperphosphatemia by blood purification is a complex issue and currently there are only a small number of studies regarding it." (PMID 24669256, 2014). "Targeted ablation of the fgf-23 gene in mice disrupts calcium, phosphorus and 1,25 (OH)2D homeostasis, giving rise to hypercalcemia, hyperphosphatemia and increased serum 1,25(OH)2D concentrations, the latter due to significantly increased renal expression of CYP27B1 mRNA and protein." (PMID 24019880, 2013). "Second, we hypothesized that elevated fibroblast growth factor 23 (FGF-23) concentrations, hyperphosphatemia, and anemia would be associated with higher hs-TnT independently of eGFR." (PMID 24148285, 2013). "Notably, FGF23 is increased early in the course of kidney disease, well before the development of hyperphosphatemia and high FGF23 levels are thus considered to be among the earliest markers of disordered phosphorus metabolism in CKD." (PMID 23339433, 2013). "Interestingly, Dmp1−/−kl/kl mice show a dramatic improvement of rickets and an identical serum biochemical phenotype to kl/kl mice (extremely high FGF23, hyperphosphatemia and reduced parathyroid hormone (PTH) levels)." (PMID 22879941, 2012). "In the absence of renal dysfunction, however, FGF23 deficiency is characterized by hyperphosphatemia and ectopic calcifications." (PMID 22590632, 2012). "During the early stages of CKD, increased FGF-23 production enhances urinary phosphate excretion and thus prevents the development of hyperphosphatemia, reduces the circulating levels of 1,25(OH)2D3, and therefore contributes to the development of secondary hyperparathyroidism." (PMID 20593414, 2010). "Furthermore, complete neutralization of FGF23 in animal models of CKD caused increased mortality, likely by severely impairing the body’s compensatory mechanism for phosphate excretion and leading to profound hyperphosphatemia." (PMID 41515987, 2025). "Therefore, the rise in circulating FGF23 is likely secondary to TAC-induced hyperphosphatemia." (PMID 41152461, 2025). "However, we have previously shown that global Fgf23 knockout mice that have hyperphosphatemia and inflammation, exhibit increased erythropoiesis and hematopoietic stem cells not only postnatally but also prenatally, indicating that FGF23 can act directly on the erythroid progenitors." (PMID 39666728, 2024). "Therefore, hyperphosphatemia may increase FGF23 levels, leading to anemia, cardiovascular disease, and eventually death, resulting in a poor renal progression." (PMID 37859858, 2023). "Fibroblast growth factor 23 (FGF23), which is a hormone secreted by osteocytes, controls the rate of urinary excretion of phosphate and inhibits renal production of 1,25-dihydroxyvitamin D. This process helps to mitigate hyperphosphatemia in patients with kidney disease." (PMID 36895836, 2023). "Furthermore, FGF-23 may increase prior to hyperphosphatemia to avoid increases in the phosphorus concentrations." (PMID 37893926, 2023). "Since high levels of serum phosphate in CKD patients are accompanied by elevated FGF23 to combat hyperphosphatemia, we added FGF23 treatments to our phosphate + CSE treatments to see whether their previously shown proinflammatory responses were further exaggerated." (PMID 36966182, 2023).
hyperphosphatemia (continued). "In summary, although the data are not totally consistent, chronic ingestion of a high phosphate diet over prolonged periods may induce hyperphosphatemia both in human subjects and mice with normal renal function, despite increases in FGF23 and PTH and a decrease in calcitriol in the blood." (PMID 35511366, 2022). "Therefore, it could be considered that FGF23 provides protection against hyperphosphatemia due to oral phosphate loading." (PMID 36084108, 2022). "Interestingly, the mRNA levels of Fgf23, a bone-derived hormone produced by osteocytes and osteoblasts in response to hyperphosphatemia, were remarkably increased by approximately 7-fold in nephrectomized BKO mice compared to nephrectomized WT following PBS intake." (PMID 35622784, 2022). "Hyperphosphatemia in CKD, which results from the disruption of phosphate excretion and renal ultrastructural damage, also increases odds for adverse renal and cardiovascular outcomes, and in dialysis patients, elevated circulating FGF23 is also an independent risk factor for mortality." (PMID 35656701, 2022). "Thus, we hypothesized that FGF‐23 predicts development of hyperphosphatemia in normophosphatemic dogs with CKD." (PMID 34418162, 2021). "However, hyperphosphatemia reduces vitamin D activity in the kidney and develops calcitriol (active metabolite of vitamin D) insufficiency that leads to defective bone mineralization and fragility, whereas hyperphosphatemia stimulates FGF-23 production in the bones." (PMID 34692259, 2021). "However, in our model, it was not possible to identify whether this occurred as a direct effect of phosphate overload or because of abnormalities in PTH and FGF-23 levels, induced by hyperphosphatemia." (PMID 34357974, 2021). "Therefore, we hypothesized that FGF‐23 would be predictive of the subsequent development of hyperphosphatemia in dogs with normophosphatemic CKD." (PMID 34418162, 2021). "When hyperphosphatemia is secondary to hypoparathyroidism, FGF23 levels usually increase to try to inhibit tubular phosphate reabsorption, as also illustrated there with increased FGF23 levels (that may also have been increased by active vitamin D analogs)." (PMID 34820344, 2021). "Therefore, hyperphosphatemia treatment with sucroferric oxyhydroxide may safely improve serum phosphorus level, renal anemia, FGF23, and other factors that affect the prognosis of hemodialysis patients." (PMID 29884226, 2018). "However, since only some of the studied animal models with elevated FGF23 develop kidney injury or hyperphosphatemia, while all of them show increases in serum concentrations of inflammatory cytokines, it is possible that FGF23 acts as a major driver of inflammation in CKD." (PMID 29770125, 2018). "As FGF-23 concentration reflects phosphorus accumulation in CKD patients, and because hyperphosphatemia increases significantly the CVD risk, FGF-23 may be a better predictor of CKD progression (time to doubling of serum creatinine) than calcium or phosphate levels." (PMID 28828171, 2017). "Consequently, the precise mechanisms by which hyperphosphatemia functions to mitigate the FGF-23's effects, the signaling pathways involved by which FGF-23 increase eNOS and NO production, and other significant endogenous α-Klotho mediated signaling functions will require further studies." (PMID 28463984, 2017). "Therefore, HDF may be an effective method for clearing serum FGF-23 in MHD patients exhibiting hyperphosphatemia." (PMID 24669256, 2014). "Even before the development of overt hyperphosphatemia, phosphorus dietary phosphorus load in CKD leads to an increase in FGF-23 and PTH, key factors driving the development of CKD-MBD." (PMID 40362897, 2025). "Genetically modified mice overexpressing FGF23 developed tubular damage, fibrosis, and fully mature TLS only in the presence of HPD‐induced hyperphosphatemia." (PMID 41384828, 2025).
hyperphosphatemia (continued). "Low calcitriol, high fibroblast growth factor 23 (FGF23), chronic hypocalcemia, and hyperphosphatemia lead to SHPT with hyperplastic transformation of the parathyroids, renal osteodystrophy, and vascular calcifications." (PMID 38893652, 2024). "In CKD, reduced glomerular filtration of phosphate is initially counteracted by the phosphaturic hormones fibroblast growth factor 23 (FGF23) and parathyroid hormone (PTH), before these compensatory mechanisms are overwhelmed and hyperphosphatemia ensues." (PMID 39399492, 2024). "A response of systemic endocrine factors (i.e., parathyroid hormone (PTH) and fibroblast growth factor 23 (FGF23)) counterbalances renal phosphate retention and delays hyperphosphatemia at earlier CKD stages." (PMID 37108433, 2023). "In vitro application of phosphate alone increased the expression of LVH-related markers and treatment with phosphate binder improved hyperphosphatemia and LVH, although serum FGF23 levels remained higher in CKD mice." (PMID 38174329, 2023). "FGF-23 belongs to the same family of FGF-21 and acts as an endocrine nexus between hormones and mineral ions with the result of preventing hyperphosphatemia and hyper-vitaminosis." (PMID 37409233, 2023). "They described fibroblast growth factor 23 (FGF-23) as the first factor to rise, followed by hyperphosphatemia and hyperparathyroidism across the CKD stages." (PMID 36873652, 2023). "Compared to the mice fed a standard phosphate diet, mice on a high phosphate diet developed hyperphosphatemia (on average 0.5 mM (26%) higher), clearly higher PTH levels and a tendency to higher FGF23 levels." (PMID 35511366, 2022). "This is evidenced by studies in which FGF23 neutralizing antibodies were given to rats with CKD, where the reduction of FGF23 resulted in hyperphosphatemia and significantly worsen vascular calcification." (PMID 36699036, 2022). "FGF-23, an osteocyte-secreted phosphaturic hormone, rises in early stages of CKD to prevent hyperphosphatemia." (PMID 35566509, 2022). "It has been illustrated that FGF23 levels increase with CKD progression, and high FGF23 levels have a compensatory effect, enhancing uric phosphate excretion to respond to hyperphosphatemia." (PMID 35656113, 2022). "Increased serum phosphate is known to affect bone metabolism directly and indirectly through the development of adaptive hormonal mechanisms aimed at preventing hyperphosphatemia, such as the increase in PTH and FGF23 and the reduction in calcitriol." (PMID 35080671, 2022). "It has been established that the phosphatonin fibroblast growth factor-23 (FGF-23) has a central role in the regulation of phosphate-vitamin D homeostasis, as this FGF-23 concentration increases secondary to hyperphosphatemia in CKD." (PMID 36304157, 2022). "Hyperphosphatemia in BKO mice increased serum erythropoietin, FGF23, and PTH levels, nominating these factors as candidate mediators of bone loss in thalassemic mice with CKD during phosphate retention." (PMID 35622784, 2022). "Increased circulating plasma FGF23 concentrations are already present in early CKD stages, long before the occurrence of hyperphosphatemia." (PMID 34371838, 2021). "Studies on animal models demonstrated that CKD-MBD, apart from elevated levels of FGF23, PTH, reduced Klotho hyperphosphatemia, osteodystrophy, vascular calcification, and cardiac hypertrophy, was characterized by the stimulation of ActRIIA." (PMID 34208727, 2021). "Our purpose was to investigate the relationship between FGF‐23 concentration and subsequent development of hyperphosphatemia and progression of CKD and determine the clinical relevance of increased FGF‐23 concentration in normophosphatemic dogs with CKD." (PMID 34418162, 2021). "When GFR further decreases, decompensation of FGF‐23 occurs because of exacerbated phosphate excretory failure and decreased klotho protein, and patients with CKD develop hyperphosphatemia." (PMID 34418162, 2021).
hyperphosphatemia (continued). "The main limitation was the impossibility of disentangling the effect of hyperphosphatemia from other CKD-MBD-related abnormalities, such as the elevation of PTH and FGF-23." (PMID 34357974, 2021). "The phenotypes appear to be independent of genetic/molecular etiology, suggesting hyperphosphatemia or FGF23 deficiency may be the pathomechanistic driver, with prominent effects on root and pulp structures, consistent with a role of phosphate and/or FGF23 in tooth development." (PMID 33977199, 2021). "A high phosphate diet was required to induce severe hyperphosphatemia as well as marked elevation of PTH and FGF‐23 in the CKD rats." (PMID 33190417, 2020). "CKD was confirmed by decreased creatinine clearance, development of interstitial kidney fibrosis, hyperphosphatemia, high plasma levels of PTH and FGF23 and low levels of plasma calcitriol and αKlotho." (PMID 32150864, 2020). "Commonly encountered dysregulation in mineral metabolism during AKI includes hypocalcemia, hyperphosphatemia, elevated parathyroid hormone (PTH), decreased 1,25-dihydroxyvitamin D (1,25D), elevated fibroblast growth factor 23 (FGF23), and decreased klotho." (PMID 33634055, 2020). "Hyperphosphataemia increases the secretion of PTH by the parathyroid glands and FGF23 by osteocytes, osteoblasts, and osteoclasts." (PMID 32132645, 2020). "The phosphaturic activity of FGF23 is critical in CKD, preventing and delaying hyperphosphatemia and vascular calcifications as FGF23 progressively rises with the loss of renal function." (PMID 32982979, 2020). "Serum FGF23 levels increase very early during CKD, considering the late development of hyperphosphatemia." (PMID 30970562, 2019). "According to the current knowledge, elevated FGF23 levels contribute to the development of LVH, whereas hyperphosphatemia primarily induces vascular calcification." (PMID 31698866, 2019). "In the first stages of CKD the phosphorus homeostasis (especially the phosphate concentration in plasma) is maintained by PTH and FGF23, but when GFR continues to fall (GFR < 50 mL/min) compensatory mechanisms fail leading to hyperphosphatemia." (PMID 29393923, 2018). "The prevalence of high FGF23 levels (≥95th percentile) was 60% in CKD and 42% in CKD-T patients, despite a low prevalence of hyperphosphatemia and normal Klotho levels." (PMID 28795324, 2018). "FGF23 has been targeted directly with antibodies in CKD rats with hyperparathyroidism, but unfortunately, the results showed a worsening of hyperphosphatemia and vascular calcification." (PMID 29808090, 2018). "Although, hyperphosphatemia is observed only in advanced CKD, serum FGF23 levels start rising early in the course of the disease, and reach extremely high levels in patients on dialysis." (PMID 30087898, 2018). "As renal function declines patients uniformly develop hyperphosphatemia, increased levels of parathyroid hormone (PTH) and fibroblast growth factor 23 (FGF23)." (PMID 29263429, 2017). "Notably, while our results showed that high phosphate significantly decreased the expression of α-Klotho, low levels of α-Klotho protein could still be detected in HAECs; thus the precise mechanism by which hyperphosphatemia functions to mitigate the FGF-23’s effects requires further studies." (PMID 28463984, 2017). "The results showed reduced hemoglobin, hyperphosphatemia, increased plasma PTH and FGF-23, and decreased plasma 25OH-D3 and 1,25-(OH)2D3 concentrations." (PMID 27658028, 2016). "Primary tumoral calcinosis without hyperphosphatemia is the most common clinical subtype, but approximately 30% of cases are familial and associated with hyperphosphatemia due to the mutation of a gene that encodes fibroblast growth factor-23 or N-acetyl-galactosaminyl transferase enzyme." (PMID 26266068, 2015).
hyperphosphatemia (continued). "As well as the known acute effects of OSP (hyperphosphatemia, hypocalcemia and APN), the effects of OSP on serum PTH and FGF-23 levels and on the expression of NaPi co-transporter proteins in the kidney (NaPi-2a) were investigated." (PMID 25790436, 2015). "Most important, epidemiological studies have shown that increased levels of FGF-23, PTH and low levels of 1,25(OH)2D3 are features that precede hyperphosphatemia during progression to CKD." (PMID 25222475, 2014). "Most patients develop hyperphosphatemia only at CKD stages 4 and 5, despite the progressive elevation of serum PTH and FGF23 levels as a defense mechanism to prevent an increase in serum phosphate levels." (PMID 23339433, 2013). "In contrast, in the NaPi-IIb−/− mouse there was only partial amelioration of hyperphosphatemia in adenine-induced CKD, and additional treatment with sevelamer was required to prevent this and reduce FGF-23 levels [34▪▪]." (PMID 23666413, 2013). "Serum FGF-23 (fibroblast growth factor) levels increase as soon as the GFR decreases below 60 mL/min, even before the development of hyperphosphatemia and hyperparathyroidism." (PMID 23819070, 2013). "Failure to secrete FGF-23 results in low serum concentrations of FGF-23, which, in turn, results in hyperphosphatemia due reduced renal Pi excretion." (PMID 18288501, 2008). "Indeed, high FGF23 levels frequently coexist with other parameters of CKD-MBD, including hyperphosphatemia (which stimulates FGF23 production), hypo- and hypercalcemia, and SHPT, long-known predictors of CV mortality." (PMID 41515987, 2025). "It is also not surprising that impairments in the phosphaturic FGF23-klotho system lead to hyperphosphatemia, as shown in genetic mouse models that lack FGF23 (Fgf23−/−) or klotho (kl/kl), which both develop severe ectopic calcifications in the absence of kidney injury." (PMID 40471241, 2025). "A reduced response to FGF-23 in the kidneys would blunt its phosphaturic effect and enhance intestinal phosphate absorption due to the inability of FGF-23 to inhibit vitamin D activation, thus perpetuating hyperphosphatemia and its adverse consequences." (PMID 40362897, 2025). "Moreover, hypocalcemia and hyperphosphatemia, which develop in CKD and are exacerbated in ESKD, can trigger secondary hyperparathyroidism and upregulate FGF23." (PMID 41373702, 2025). "The temporal changes of disordered mineral metabolism in CKD patients are well‐established, with a progressive rise in circulating fibroblast growth factor (FGF) 23 (FGF23) early in the course of CKD, followed by secondary hyperparathyroidism and hyperphosphataemia in the late stages." (PMID 40464156, 2025). "Moreover, LVH is a consequence of alterations in mineral metabolism andspecifically of the increase in FGF-23 induced by an increase in parathormone(PTH) and hyperphosphatemia." (PMID 39076335, 2024). "Hypocalcemia, hyperphosphatemia, and decreased serum 1,25-dihydroxyvitamin D (1,25(OH)2D) can stimulate the secretion of PTH, while elevated serum calcium, 1,25(OH)2D or fibroblast growth factor 23 (FGF23) can inhibit PTH secretion." (PMID 39829956, 2024). "Also, hyperphosphatemia and increased PTH and calcitriol activity increase the production of fibroblast growth factor 23 (FGF23) from osteocystic cells in bone, which is responsible for the decrease in P renal reabsorption." (PMID 38613476, 2024). "On the other hand, FGF23 cleavage is decreased in patients with CKD and during hyperphosphatemia." (PMID 37681408, 2023). "The mechanism behind this relationship is unclear; it has been suggested that the increase in FGF-23, following the increase in PTH and hyperphosphatemia, may induce a worsening of renal function and a progression towards dialysis." (PMID 36678208, 2023).